ACAT1 (acetyl-CoA acetyltransferase 1)
Diseases named in the same sentence as ACAT1 in open-access papers (continued):
Sharing a sentence is not in itself a finding about the gene and the disease.
hyperlipidemia (5 papers, 2012 to 2023). "Further studies in hyperlipidemia models showed that the detrimental effects of ACAT-1 deficiency were attributed to increased macrophage apoptosis caused by a massive accumulation of free cholesterol and impaired cellular cholesterol efflux." (PMID 24577316, 2014). "In the present study, the associations of ACAT-1 rs1044925 SNP and serum lipid levels were determined according to the subjects with or without hyperlipidemia." (PMID 22243772, 2012). "In addition, previous studies have found the ACAT-1 gene polymorphisms affect serum HDL-C levels in endogenous hypertriglyceridemia, as well as hyperlipidemia." (PMID 22243772, 2012). "miR-21a-5p improved hyperlipidemia via the inhibition of its targets FABP7, 3-hydroxy-3-methylglutaryl CoA reductase (HMGCR), acetyl CoA acetyltransferase 1 (ACAT1), and oxidized low-density lipoprotein receptor 1 (OLR1)." (PMID 39872853, 2023). "Our work identified miR-21a-5p as a potential regulator of aerobic exercise affecting lipid metabolism, achieved the favorable goal in hyperlipidemia by synergistically inhibiting the expression of target genes FABP7, HMGCR, ACAT1, and OLR1." (PMID 34099844, 2021). "And we think one of the mechanisms by which aerobic exercise improved hyperlipidemia was to up-regulate the expression of miR-21a-5p, thus inhibited the expression of target genes FABP7, HMGCR, ACAT1, and OLR1, which were closely related to lipid metabolism." (PMID 34099844, 2021). "Taken together, these results demonstrated that aerobic exercise improved hyperlipidemia through miR-21a-5p-induced inhibition of target genes FABP7, HMGCR, ACAT1, and OLR1." (PMID 34099844, 2021). "We found that the effect of ACAT-1 rs1044925 SNP on serum TC, HDL-C and ApoAI was more prominent in subjects with hyperlipidemia than in subjects with normolipidemia." (PMID 22243772, 2012). "The only result directly present in our study was that the ACAT-1 rs1044925 SNP influenced the HDL-C and ApoAI levels in the male with hyperlipidemia, which suggests that the ACAT-1 rs1044925 SNP might influence the cellular cholesterol efflux in the male hyperlipidemic subjects." (PMID 22243772, 2012).
colon carcinoma (4 papers, 2018 to 2024). "In the present study, we found that blood insulin levels was associated with ACAT1 expression and clinic pathological characteristics, then we observed insulin improved cell proliferation and migration of colon cancer HT29 cells in a time and dose-dependent manner." (PMID 29793481, 2018). "In future studies, we will confirm our results in other colon cancer cell lines, and search for potential molecular targets of ACAT1 and identify them." (PMID 29793481, 2018). "To substantiate the role of ACAT1 in colon cancer growth and metastasis promoted by insulin, we used ACAT1 siRNA to inhibit ACAT1 gene expression in HT-29 cells as described in Materials and Methods." (PMID 29793481, 2018). "In our previous studies we found that ACAT1 is overexpressed in colon cancer tissues compared with the paired adjacent normal tissues, which suggests that ACAT1 is involved in the pathogenesis of colon cancer." (PMID 29793481, 2018). "Another study reported that the gene of ACAT1 was downregulated in colon cancer." (PMID 35172832, 2022). "Next, by considering the combined biomarkers, we defined two molecular metabolism phenotypes of colon cancer: a glycolysis‐proficient phenotype (glycolysis+) with either GLUT1 or PFKFB3 overexpression and a ketolysis‐deficient (ketolysis−) phenotype by null expression of either OXCT1 or ACAT1." (PMID 36031388, 2022). "However, few studies have been done on the mechanism of ACAT1 in insulin-related colon cancer." (PMID 29793481, 2018). "Therefore, insulin could promote colon cancer progression by upregulation of ACAT1, which maybe is a potential therapeutic target for colon cancer." (PMID 29793481, 2018). "According to this guideline, colon cancers can be divided into either ketolytic (G+/K+) or glycolytic (G+/K−) subtypes based on the expression of OXCT1, ACAT1, GLUT1, and PFKPF3." (PMID 36031388, 2022). "The gene expression levels of OXCT1 and ACAT1 in each colon cancer patient varied greatly, suggesting notable differences in ketolytic metabolism." (PMID 36031388, 2022). "Furthermore, although four signature molecules (OXCT1, ACAT1, GLUT1, and PFKPF3) were identified in this study to stratify the metabolic subgroups in colon cancer, they may not be the optimal set for other types of cancers." (PMID 36031388, 2022).
ketoacidosis (4 papers, 2021 to 2024). "Among these genes, acetyl-CoA acetyltransferase 1, encoded by ACAT1, is an enzyme that regulates ketone metabolism based on different energy status, and downregulation of ACAT1 is an important feature in the pathophysiology of type 2 diabetes." (PMID 33865459, 2021).
leukemia (4 papers, 2020 to 2024). A malignant (clonal) hematologic disorder, involving hematopoietic stem cells and characterized by the presence of primitive or atypical myeloid or lymphoid cells in the bone marrow and the blood. "Elevated ACAT1 activity has also been detected in head and neck cancer, lung cancer, and leukemia." (PMID 39247186, 2024). "In addition, inhibitors of Acyl Coenzyme A: Cholesterol Acyltransferases 1 (ACAT1), which also known as sterol O-acyltransferase 1 (SOAT1), could suppress tumor growth by downregulating cholesterol esterification (CE) in leukemia and triple-negative breast cancer." (PMID 37488496, 2023).
lung adenocarcinoma (4 papers, 2023 to 2025). A carcinoma that arises from the lung and is characterized by the presence of malignant glandular epithelial cells. "The expression levels of ACAT1 and ACSL3 in tissues derived from normal lung and lung adenocarcinoma (LUAD) tissues were compared by qRT‐PCR." (PMID 39323079, 2024).
nasopharyngeal carcinoma (4 papers, 2021 to 2024). A carcinoma arising from the nasopharyngeal epithelium. "Similarly, it was shown that other ketogenic enzymes such as ACAT1, HMGCL and/or BDH1/2 levels were significantly downregulated in ccRCC cells and patients, acute myeloid leukemia (AML) patients and AML cell lines, and nasopharyngeal carcinoma (NPC) cells." (PMID 36432618, 2022).
ovarian carcinoma (4 papers, 2020 to 2025). A malignant neoplasm originating from the surface ovarian epithelium. "In order to understand the molecular mechanism(s) underlying apoptosis or suppression of cancer cell proliferation upon ACAT-1/ CE inhibition in ovarian cancer cell lines, we focused on tumor suppressor genes associated with cell cycle and apoptosis." (PMID 31978092, 2020). "As per the cBioportal database, genetic alteration of ACAT1 gene was reported in 4% of ovarian cancer patients (66 of 1713 patients), most of which are copy number amplifications." (PMID 35399074, 2022). "In this study, we focused on the role of ACAT-1 and CE levels in ovarian cancer using a panel of ovarian cancer cell lines." (PMID 31978092, 2020). "In this in vitro study, we determined the expression levels and contribution of ACAT-1 in ovarian cancer progression utilizing a panel of ovarian cancer cell lines." (PMID 31978092, 2020). "Using qRT-PCR, we found significant expression of ACAT-1 mRNA in a panel of ovarian cancer cell lines compared to primary ovarian epithelial cells, H-6036 (normal controls)." (PMID 31978092, 2020). "ACAT-1 mediates esterification of cholesterol to CE for its storage in LDs; thus, we assessed the levels of TC, FC and CE in ovarian cancer cell lines." (PMID 31978092, 2020). "While the role of ACAT-1/CE accumulation is being studied in various cancers, information regarding the contribution of these mediators in ovarian cancer is relatively scarce." (PMID 31978092, 2020). "In positive correlation with ACAT-1 data, CE levels in ovarian cancer cell lines were significantly higher (5–7 fold) than normal control cells." (PMID 31978092, 2020). "We observed significant suppression of cell proliferation, migration and invasion in ACAT-1 knockdown ovarian cancer cell lines compared to their respective controls (cell lines transfected with scrambled shRNA)." (PMID 31978092, 2020). "To further understand the role of ACAT-1 in tumor progression, we performed cell viability assays using three ovarian cancer cell lines SKOV-3, OC-314 and IGROV-1." (PMID 31978092, 2020). "In this in vitro study, we assessed the expression and contribution of ACAT-1 in ovarian cancer progression." (PMID 31978092, 2020). "Similar to other cancers, this study revealed significant expression of ACAT-1 and CE in ovarian cancer cell lines compared to normal control cells." (PMID 31978092, 2020). "In summary, our results show increased expression of ACAT-1 in ovarian cancer cell lines compared to the primary ovarian epithelial cells (normal controls); thus, confirming that ACAT-1 mediated CE accumulation is a cancer specific event." (PMID 31978092, 2020). "Immunostaining data further confirmed the enhanced expression of ACAT-1 protein in ovarian cancer cell lines versus normal control cells." (PMID 31978092, 2020). "We observed a significant increase in the expression of ACAT-1 and CE levels in a panel of ovarian cancer cell lines (OC-314, SKOV-3 and IGROV-1) compared to primary ovarian epithelial cells (normal controls)." (PMID 31978092, 2020). "In comparison to ACAT-2, ACAT-1 expression varied significantly between ovarian cancer cell lines versus normal control cells." (PMID 31978092, 2020). "However, we used public databases such as the PrognoScan Online Platform and Kaplan-Meier Plotter Analysis to evaluate the prognostic value of ACAT1 expression for ovarian cancer prognosis." (PMID 35399074, 2022). "Our findings of increased CE and ACAT1 levels in epithelial ovarian cancer (EOC) cell lines prompted us to investigate whether such an increase occurs in primary clinical samples obtained from human subjects diagnosed with EOC." (PMID 35399074, 2022). "These clinical data suggest that ACAT1 expression may be a potential prognostic marker for ovarian cancer and warrants further investigation." (PMID 35399074, 2022).
ovarian carcinoma (continued). "Therefore, we specifically inhibited ACAT-1 in ovarian cancer cell lines by generating stable ACAT-1 knock down cell lines using shRNA sequences corresponding to ACAT-1." (PMID 31978092, 2020). "However, the significance of ACAT-1 and cholesterol esters (CE) is relatively understudied in ovarian cancer." (PMID 31978092, 2020). "Collectively, these results support the idea that ACAT-1 inhibition leads to enhanced apoptosis in ovarian cancer cell lines which may contribute to reduced cell proliferation." (PMID 31978092, 2020). "Therefore, therapeutic strategies to regulate ACAT-1/CE levels may prove beneficial for ovarian cancer treatments." (PMID 31978092, 2020). "Since ACAT exists predominantly in two isoforms (ACAT-1 and ACAT-2), it is essential to understand the expression levels of both isoforms in ovarian cancer cell lines." (PMID 31978092, 2020). "Acetyl-CoA acetyltransferase 1 (ACAT1) is an important enzyme as it plays a vital role in various cancers, for example, by exerting a liver and kidney tumor-promoting effect and an anti-ovarian cancer effect." (PMID 36517760, 2022). "ACAT-2 expression was not altered during the transfection implicating ACAT-1 specific knockdown in all ovarian cancer cell lines." (PMID 31978092, 2020).
uterine cancer (4 papers, 2015 to 2024). Primary or metastatic malignant neoplasm involving the uterine corpus and/or the cervix. "Drawing from previous research indicating that ACAT1 promotes proliferation and metastasis in cancers such as prostate and uterine cancer 23-27, we employed bioinformatics to establish an association between ACAT1 and both cell proliferation and EMT." (PMID 38817856, 2024). "Thus, ACAT1 is potentially to be a candidate for the diagnosis of doxorubicin-associated drug resistance in uterine cancer." (PMID 25639359, 2015). "ACAT1 was found to be upregulated in doxorubicin-resistant uterine cancer, and its knockdown correlated with inhibited migration and proliferation of cancer cells, as well as enhanced apoptosis." (PMID 38817856, 2024). "Mutations of PPP2R1A in uterine cancer affect oncogenic signaling and promote tumor cell growth, whereas EHHADH and ACAT1 are regulators of drug resistance in tumor cells; however, the role of VCP in cancer is unclear." (PMID 37373553, 2023). "ACAT1 also sensitizes doxorubicin-resistant uterine cancer cells to doxorubicin therapy." (PMID 39247186, 2024).
breast tumor (3 papers, 2023 to 2025). "It has been found that ACAT1 upregulation in breast tumor cells could promote tumor initiation and metastasis, indicating ACAT1 as a metabolic tumor promoter." (PMID 38720812, 2024).
cognitive deficits (3 papers, 2023 to 2025). "Similar observations were made in the 3×Tg-AD mouse model, in which Acat1 gene knockout results in decreased hAPP and Aβ1-42 levels and rescue of cognitive deficits." (PMID 36979106, 2023).
coronary artery disease (3 papers, 2014 to 2022). "We also found that ACAT-1 rs11545566 and rs10913733 were associated with the increased susceptibility to coronary artery disease." (PMID 29179498, 2017). "The present study was performed to clarify the association between the acyl-CoA:cholesterol acyltransferase-1 (ACAT-1) single nucleotide polymorphism (SNP) rs1044925 and the risk of coronary artery disease (CAD) and ischemic stroke (IS) in the Guangxi Han population." (PMID 24577316, 2014). "Therefore, the present study aimed to determine whether the ACAT-1 SNP rs1044925 is associated with the risk of coronary artery disease (CAD) and ischemic stroke (IS)." (PMID 24577316, 2014). "The aim of present study was to investigate whether there exists a possible correlation between genetic variations in ACAT-1 genes and coronary artery disease (CAD) risk." (PMID 29179498, 2017).
lipid metabolism disorder (3 papers, 2021 to 2025). "Dictamnine also increased intracellular lipid metabolism disorder via the down-regulation of ACAT1 and FABP-1 and up-regulation of ACSL4." (PMID 34595163, 2021). "Besides, the up-regulation of Acyl-CoA synthetase long-chain family member 4 (ACSL4) and down-regulation of acetyl-coa acetyltransferase 1 (ACAT1) and fatty acid binding protein 1 (FABP-1) proteins were linked to lipid metabolism disorder." (PMID 34595163, 2021). "Thus, dictamnine inhibits the ACAT1 and FABP-1expression and activates ACSL4 expression, which collectively contributes to lipid metabolism disorder and the progression of hepatotoxicity." (PMID 34595163, 2021). "This study provides convincing evidence that JHP may partially ameliorate early NONFH by restoring the balance of lipid metabolism disorder and reversing pathological events during early NONFH progression by regulating the NAMPT/STK11/HMGCR/ACAT1 axis." (PMID 40988117, 2025).
renal carcinoma (3 papers, 2015 to 2025). A carcinoma arising from the epithelium of the renal parenchyma or the renal pelvis. "ACAT1 overexpression suppresses proliferation and migration of human renal carcinoma cells in vitro." (PMID 39403185, 2024). "Only one report shows that ACAT1 is a potential diagnostic cancer marker for renal carcinoma 27 with no report in drug resistant field." (PMID 25639359, 2015). "Given the strong link between renal cancer and metabolism, we prioritized SLC25A5, HEL-S-87p and ACAT1 as our metabolic targets." (PMID 40790033, 2025).
amyloid (2 papers, 2023 to 2025). "Since then, it has been shown that reducing ACAT1/SOAT1 activity by genetic manipulation or small molecule inhibition reduces amyloid pathology and rescues deficits seen in mouse models of AD." (PMID 36982602, 2023). "Blocking ACAT1/SOAT1 activity by genetic ablation or pharmacological inhibition has been shown to reduce amyloid pathology in mice by lowering levels of the amyloid precursor protein (APP) and its toxic product, Aβ." (PMID 36982602, 2023).
Bladder cancer (2 papers, 2024). "However, the biological role of ACAT1 in bladder cancer (BLCA) has yet to be elucidated." (PMID 38817856, 2024). "Bladder cancer (BLCA) cells contain higher levels of cholesterol content compared to normal cells, and acyl-coenzyme A (CoA): cholesterol acyltransferase-1 (ACAT1) plays a crucial role in the esterification of cholesterol." (PMID 38169575, 2024).
cervical cancer (2 papers, 2024 to 2025). A primary or metastatic malignant neoplasm involving the cervix. "In cervical cancer, ACAT1 acetylates Parkin to promote mitophagy and inhibit proliferation, whereas HDAC2 deacetylates Parkin to block its function and accelerate progression." (PMID 41213956, 2025). "In cervical cancer, ACAT1 acetylates Parkin to promote mitophagy and maintain mitochondrial homeostasis, correlating with favorable prognosis." (PMID 41213956, 2025).
Cushing syndrome (2 papers, 2018 to 2022). Cushing's syndrome (CS) encompasses a group of hormonal disorders caused by prolonged and high exposure levels to glucocorticoids that can be of either endogenous (adrenal cortex production) or exogenous (iatrogenic) origin. "ATR-101, an ACAT1 inhibitor, is effective in the treatment of Cushing’s syndrome in dogs." (PMID 36361592, 2022). "ATR-101, a selective inhibitor of ACAT1 (acyl coenzyme A:cholesterol acyltransferase 1), is a novel small molecule therapeutic currently in clinical development for the treatment of adrenocortical carcinoma, congenital adrenal hyperplasia, and Cushing’s syndrome in humans." (PMID 29720169, 2018).
dementia (2 papers, 2016 to 2021). Loss of intellectual abilities interfering with an individual's social and occupational functions. "Humans ACAT1/SOAT1 genetic variant analyses also support the role of ACAT1 in modulating dementia susceptibility." (PMID 33841127, 2021). "Among the 2384 unique gene correlates of Gsto1 expression in hippocampus are 128 genes that share a high co-incidence of literature citations—24 of which are known to be associated with AD or dementia, including well studied candidates Chmp2b, Optn, Dlst, Sod2, and Acat1." (PMID 26829228, 2016).